ENSG00000284820 (novel protein)
Gene: Protein-coding gene on chromosome 2 (219,209,772 to 219,222,738, reverse strand). Ensembl gene ENSG00000284820.
Genetic constraint (gnomAD): Missense variants: 318 observed, 344.02 expected, observed/expected ratio (o/e) 0.92, 90% interval 0.84 to 1.01. Synonymous variants: 116 observed, 140.51 expected, observed/expected ratio (o/e) 0.83, 90% interval 0.71 to 0.96.